RPS6KA1 (ribosomal protein S6 kinase A1)
Description:
Serine/threonine-protein kinase that acts downstream of ERK (MAPK1/ERK2 and MAPK3/ERK1) signaling and mediates mitogenic and stress-induced activation of the transcription factors CREB1, ETV1/ER81 and NR4A1/NUR77, regulates translation through RPS6 and EIF4B phosphorylation, and mediates cellular proliferation, survival, and differentiation by modulating mTOR signaling and repressing pro-apoptotic function of BAD and DAPK1. In fibroblast, is required for EGF-stimulated phosphorylation of CREB1, which results in the subsequent transcriptional activation of several immediate-early genes. In response to mitogenic stimulation (EGF and PMA), phosphorylates and activates NR4A1/NUR77 and ETV1/ER81 transcription factors and the cofactor CREBBP. Upon insulin-derived signal, acts indirectly on the transcription regulation of several genes by phosphorylating GSK3B at 'Ser-9' and inhibiting its activity. Phosphorylates RPS6 in response to serum or EGF via an mTOR-independent mechanism and promotes translation initiation by facilitating assembly of the pre-initiation complex. In response to insulin, phosphorylates EIF4B, enhancing EIF4B affinity for the EIF3 complex and stimulating cap-dependent translation. Is involved in the mTOR nutrient-sensing pathway by directly phosphorylating TSC2 at 'Ser-1798', which potently inhibits TSC2 ability to suppress mTOR signaling, and mediates phosphorylation of RPTOR, which regulates mTORC1 activity and may promote rapamycin-sensitive signaling independently of the PI3K/AKT pathway. Also involved in feedback regulation of mTORC1 and mTORC2 by phosphorylating DEPTOR. Mediates cell survival by phosphorylating the pro-apoptotic proteins BAD and DAPK1 and suppressing their pro-apoptotic function. Promotes the survival of hepatic stellate cells by phosphorylating CEBPB in response to the hepatotoxin carbon tetrachloride (CCl4). Mediates induction of hepatocyte prolifration by TGFA through phosphorylation of CEBPB. Is involved in cell cycle regulation by phosphorylating the CDK inhibitor CDKN1B, which promotes CDKN1B association with 14-3-3 proteins and prevents its translocation to the nucleus and inhibition of G1 progression. Phosphorylates EPHA2 at 'Ser-897', the RPS6KA-EPHA2 signaling pathway controls cell migration. In response to mTORC1 activation, phosphorylates EIF4B at 'Ser-406' and 'Ser-422' which stimulates bicarbonate cotransporter SLC4A7 mRNA translation, increasing SLC4A7 protein abundance and function. (Microbial infection) Promotes the late transcription and translation of viral lytic genes during Kaposi's sarcoma-associated herpesvirus/HHV-8 infection, when constitutively activated.
Synonyms: MAPKAPK1A; RSK1; HU-1; p90Rsk; MAPKAPK1; RSK
Tractability: Small molecule: a drug acting on it is in phase 1 trials; a structure with a bound ligand is known; a high-quality ligand is known; it has a high-quality binding pocket; it belongs to a druggable protein family. PROTAC: it is named in the literature on targeted protein degradation; ubiquitination databases record sites on it; its protein half-life has been measured; a small molecule that binds it is known.
Target class: Enzyme; Kinase; AGC protein kinase group; AGC protein kinase RSK subfamily; Protein Kinase; AGC protein kinase RSK family
Chemical probes: BAY-3827 (high quality), BI-D1870, BI00645435 (high quality)
Gene: Protein-coding gene on chromosome 1 (26,529,756 to 26,575,030, forward strand). Ensembl gene ENSG00000117676.
Subcellular location: Nucleus; Cytoplasm
Subcellular location (Human Protein Atlas): Cytosol; Nucleoplasm
Pathways (Reactome):
Signal Transduction: CREB phosphorylation; ERK/MAPK targets; Gastrin-CREB signalling pathway via PKC and MAPK
Developmental Biology: Recycling pathway of L1; Transcriptional and post-translational regulation of MITF-M expression and activity
Neuronal System: CREB1 phosphorylation through NMDA receptor-mediated activation of RAS signaling; RSK activation
Cellular responses to stimuli: Senescence-Associated Secretory Phenotype (SASP)
Gene Ontology:
Molecular function: mitogen-activated protein kinase binding; PDZ domain binding; protein binding; protein serine/threonine kinase activity; protein serine/threonine/tyrosine kinase activity; ribosomal protein S6 kinase activity; ATP binding; magnesium ion binding; protein kinase activity; protein serine kinase activity
Biological process: negative regulation of apoptotic process; negative regulation of TOR signaling; positive regulation of hepatic stellate cell activation; positive regulation of transcription by RNA polymerase II; protein phosphorylation; chemical synaptic transmission; hepatocyte proliferation; positive regulation of cell differentiation; positive regulation of cell growth; positive regulation of DNA-templated transcription; regulation of DNA-templated transcription; regulation of translation in response to stress; signal transduction; TORC1 signaling; intracellular signal transduction
Cellular component: cytosol; nucleoplasm; cytoplasm; nucleus; synapse
Genetic constraint (gnomAD): Loss-of-function variants: 46 observed, 84.69 expected, observed/expected ratio (o/e) 0.54, 90% interval 0.43 to 0.69. The upper end of that interval is the gene's LOEUF score, 0.69, which puts it in group 2 of 6, group 1 being the genes least tolerant of losing a copy. Missense variants: 684 observed, 937.31 expected, observed/expected ratio (o/e) 0.73, 90% interval 0.69 to 0.78. Synonymous variants: 337 observed, 373.57 expected, observed/expected ratio (o/e) 0.9, 90% interval 0.82 to 0.99.
Homologues: Orthologues: dog RPS6KA1 (99% identical), mouse Rps6ka1 (99% identical), chimpanzee RPS6KA1 (97% identical), macaque RPS6KA1 (96% identical), pig RPS6KA1 (95% identical), guinea pig RPS6KA1 (95% identical), rat Rps6ka1 (94% identical), rabbit RPS6KA1 (93% identical), tropical clawed frog rps6ka1 (85% identical), zebrafish rps6ka1 (85% identical), Caenorhabditis elegans rskn-2 (36% identical), Drosophila melanogaster JIL-1 (34% identical), and 4 more. Paralogues in human: RPS6KA3 (79% identical), RPS6KA2 (77% identical), RPS6KA6 (73% identical), RPS6KA5 (42% identical), RPS6KA4 (41% identical), RPS6KB1 (30% identical), RPS6KB2 (27% identical).